PHLDB3 (pleckstrin homology like domain family B member 3)
Synonyms: FLJ40193
Tractability: Antibody: the Human Protein Atlas places it where antibodies can reach. PROTAC: ubiquitination databases record sites on it.
Gene: Protein-coding gene on chromosome 19 (43,473,625 to 43,505,301, reverse strand). Ensembl gene ENSG00000176531.
Subcellular location (Human Protein Atlas): Nuclear speckles; Cytosol; Plasma membrane
Gene Ontology:
Molecular function: enzyme binding
Genetic constraint (gnomAD): Loss-of-function variants: 86 observed, 71.73 expected, observed/expected ratio (o/e) 1.2, 90% interval 1.01 to 1.43. The synonymous counts are far from expectation, so gnomAD's model fits this gene poorly and the ratio says little. Missense variants: 987 observed, 789.91 expected, observed/expected ratio (o/e) 1.25, 90% interval 1.18 to 1.32. Synonymous variants: 373 observed, 310.22 expected, observed/expected ratio (o/e) 1.2, 90% interval 1.1 to 1.31.
Homologues: Orthologues: chimpanzee PHLDB3 (99% identical), macaque PHLDB3 (95% identical), pig PHLDB3 (84% identical), dog PHLDB3 (80% identical), mouse Phldb3 (79% identical), rat Phldb3 (77% identical), tropical clawed frog phldb3 (37% identical), Drosophila melanogaster dos (11% identical), Caenorhabditis elegans soc-1 (6% identical). Paralogues in human: PHLDB1 (36% identical), PHLDB2 (35% identical), GAB1 (7% identical), GAB2 (7% identical), PLEKHS1 (6% identical), GAB4 (6% identical), GAB3 (6% identical).
Diseases named in the same sentence as PHLDB3 in open-access papers:
PHLDB3 is named in the same sentence as 12 diseases in open-access papers, as found by Europe PMC text mining. Sharing a sentence is not in itself a finding about the gene and the disease. The quoted sentences say what the papers report.
colon cancer (2 papers, 2016 to 2022). "As anticipated above, PHLDB3 silencing led to marked reduction of colon cancer cell viability, which was more significant in HCT116p53+/+ cells than in HCT116p53−/− cells." (PMID 28008906, 2016).
colorectal cancer (1 paper, 2016). A primary or metastatic malignant neoplasm that affects the colon or rectum.
esophageal cancer (1 paper, 2016). A primary or metastatic malignant neoplasm involving the esophagus.
gastric cancer (1 paper, 2016). A primary or metastatic malignant neoplasm involving the stomach. "Remarkably, our further relevance analysis of gastric cancer database showed that patients with higher PHLDB3 expression display a much shorter disease-free survival rate than patients with lower PHLDB3 expression." (PMID 28008906, 2016).
cancer (3 papers, 2016 to 2020). A tumor composed of atypical neoplastic, often pleomorphic cells that invade other tissues. "Analysis of cancer genomic databases reveals that PHLDB3 is amplified and/or highly expressed in numerous human cancers." (PMID 28008906, 2016). "To further confirm the effect of PHLDB3 on cancer cell survival, we generated HCT116 cell lines that stably express PHLDB3 shRNA." (PMID 28008906, 2016). "Indeed, our results as shown here demonstrate that PHLDB3 depletion leads to elevated apoptosis and increases the sensitivity of cancer cells to therapeutic drugs." (PMID 28008906, 2016). "To test this possibility, we first investigated whether downregulation of PHLDB3 expression by siRNA would affect cancer cell apoptosis." (PMID 28008906, 2016).
tumor (3 papers, 2016 to 2020). "At the end of the experiment, the average tumour weight with PHLDB3 depletion was smaller than that with scramble shRNA." (PMID 28008906, 2016). "PHLDB3 depletion more markedly slowed down the growth of xenograft tumour derived from HCT116p53+/+ cells than that from HCT116p53−/− cells." (PMID 28008906, 2016). "Moreover, ectopic PHLDB3 promotes cell growth and inhibits apoptosis in both cell-based and xenograft tumour models." (PMID 28008906, 2016). "Therefore, future efforts need to address if PHLDB3 modulates the AKT pathway and if this provides an advantage for tumor survival." (PMID 32429563, 2020).
PHLDB3 also shares sentences with these, for which no sentence is quoted: breast carcinoma (1 paper); breast invasive carcinoma (1); liver cancer (1); lung carcinoma (1); non-small cell lung carcinoma (1); sarcoma (1).